GLIS3 (GLIS family zinc finger 3)
Diseases named in the same sentence as GLIS3 in open-access papers (continued):
Sharing a sentence is not in itself a finding about the gene and the disease.
glioblastoma (5 papers, 2016 to 2022). The most malignant astrocytic tumor (WHO grade IV). "GLIS3 has been reported to be highly expressed in ependymomas and glioblastomas, suggesting a role for GLIS3 in tumorigenesis." (PMID 27172792, 2016). "CAPG was identified to be up-regulated in glioblastoma cell lines in previous study and GLIS3 was found to be an overexpressed gene in GBM tissues." (PMID 36114444, 2022). "The expression levels of circ_COL1A2, circ_PTN, circ_VCAN, circ_PLOD2, circ_SMO, circ_CLIP2, circ_GLIS3, and circ_EPHB4 in glioblastoma (GBM) are significantly higher than those in normal tissues." (PMID 30064463, 2018). "Eight circRNAs, including circ_COL1A2, circ_PTN, circ_VCAN, circ_SMO, circ_PLOD2, circ_GLIS3, circ_EPHB4, and circ_CLIP2 showed significantly higher expression in glioblastoma (GBM) than in normal tissues." (PMID 28969099, 2017).
glioma (5 papers, 2010 to 2025). A benign or malignant brain and spinal cord tumor that arises from glial cells (astrocytes, oligodendrocytes, ependymal cells). "Recently, expression of circular GLIS3 (circGLIS3) RNAs, generated by exon 2 or exons 5–8, have been implicated in several tumor types, including glioma, non-small cell lung cancer (NSCLC), and bladder cancer." (PMID 35681527, 2022). "A different report showed that high levels of GLIS3 expression correlated with high-grade gliomas and poor prognosis." (PMID 35681527, 2022). "Knockdown of GLIS3 expression in glioma cells lines reduced cell proliferation and migration, inhibited the activation of the NF-κB signaling pathway, and suppressed the in vivo malignant behavior of cells when implanted into nude mice." (PMID 35681527, 2022). "A few studies have referred to the correlation of the GLIS3 transcriptional level with higher grade of gliomas and with poor outcome of ependymoma, but the function and mechanism have not been discovered." (PMID 34540823, 2021). "Here, a circRNA merely upregulated in high-grade glioma, circGLIS3 (hsa_circ_0002874, originating from exon 2 of GLIS3), was validated by microarray and Real-time quantitative reverse transcription PCR (qRT-PCR)." (PMID 34540823, 2021). "Integrated DNA and RNA analysis of low-grade and high-grade proneural gliomas identified increased expression and gene amplification of several genes including GLIS3, TGFB2, TNC, AURKA, and VEGFA in proneural GBMs, with corresponding loss of DLL3 and HEY2." (PMID 20838435, 2010). "Additionally, GLIS3 in the M2 module has been studied to influence the glioma cells’ invasion, migration, and proliferation and upregulate the NF-κB signaling pathway." (PMID 37189441, 2023). "Over-expression of GLIS3 in glioma cell lines had the inverse effect." (PMID 35681527, 2022). "Besides, the ratio of circGLIS3 to GLIS3 mRNA within exosomes is increased compared with the cellular RNA ratio, indicating a selective secretion of circGLIS3 in glioma exosomes." (PMID 34540823, 2021). "Another circRNA, circ-GLIS3, a miR-548m sponge, is also up-regulated in TMZ-resistant glioma cells and facilitates glioma progression and resistance presumably through the induction of mediator of RNA polymerase II transcription subunit 31 (MED31) expression (a transcription coregulatory)." (PMID 39877636, 2025).
Obesity (5 papers, 2014 to 2025). Accumulation of substantial excess body fat. "Moreover, a number of candidate genes previously linked through GWAS to T2DM and obesity were found to be differentially expressed in the adipose tissue from discordant twins, including PPARG, GLIS family zinc finger 3 (GLIS3) (T2DM), vascular endothelial growth factor A (VEGFA), and IRS1 (obesity)." (PMID 32653024, 2020). "Furthermore, for some of the candidate genes for T2D, T2D related traits and obesity identified by GWAS, we found both differential mRNA expression and changes in DNA methylation in islets exposed to palmitate, for example, TCF7L2 and GLIS3 show decreased expression and increased DNA methylation." (PMID 24953961, 2014).
liver fibrosis (4 papers, 2016 to 2022). "Out of 19 patients with NDH syndrome due to GLIS3 mutations reported to date, exocrine pancreatic insufficiency is documented in four cases, all of which suffer from hepatic disease with liver fibrosis." (PMID 33935973, 2021). "Our top ranking feature, GLIS3, belongs to the same family with another candidate regulator, GLIS2, and, together, they have been found to be associated with liver fibrosis." (PMID 27818995, 2016).
melanoma (4 papers, 2016 to 2023). A malignant, usually aggressive tumor composed of atypical, neoplastic melanocytes. "Since PXDN, NTN4 and GLIS3 are involved in motility and associated with mesenchymal gene signature in melanoma cell lines, we investigated the association of these candidate proteins with markers of EMT in clinical samples." (PMID 27172792, 2016). "GLIS3 was also found to be upregulated in the majority of mesenchymal-like melanoma cells compared with epithelial-like melanoma cells that expressed very little or no GLIS3." (PMID 27172792, 2016). "We identified Peroxidasin (PXDN), Netrin 4 (NTN4) and GLIS Family Zinc Finger 3 (GLIS3) genes consistently elevated in invasive mesenchymal-like melanoma cells." (PMID 27172792, 2016). "Through a knockdown approach and in vivo motility model, we demonstrate 3 novel molecular players PXDN, NTN4 and GLIS3 as critical factors of melanoma invasion." (PMID 27172792, 2016). "Whole mount and cross-sections of embryos shows that fewer PXDN and GLIS3 siRNA treated melanoma cells migrated out of the neural tube compared to control siRNA treated cells in LM-MEL-77 and -46 (not shown)." (PMID 27172792, 2016). "Although this study shows an association between PXDN, NTN4, GLIS3 and SNAI1 and melanoma invasion, their roles in melanoma are most likely multifaceted." (PMID 27172792, 2016). "GLIS3 expression levels in six mesenchymal-like melanoma cells LM-MEL-12, -38, -46, -45, -59 and -77 was effectively down-regulated." (PMID 27172792, 2016). "The significant correlation between PXDN and GLIS3 expression with EMT markers that was observed in our melanoma cell line studies is therefore also confirmed in a large clinical tumor dataset." (PMID 27172792, 2016). "Given that PXDN, NTN4 and GLIS3 can regulate invasion of melanoma cells in vitro, we evaluated the in vivo relevance of our data in melanoma tumors." (PMID 27172792, 2016). "The preceding experiments indicated that PXDN, NTN4 and GLIS3 are highly expressed in metastatic melanoma and play a role in promoting melanoma cell invasion in vitro." (PMID 27172792, 2016). "We then analysed the protein expression patterns of PXDN, NTN4 and GLIS3 in melanoma tumors by immunohistochemical staining of tissue microarrays (TMA) comprising tumors from patients with stage III and IV metastatic melanoma." (PMID 27172792, 2016). "We then analyzed the invasive behaviour of melanoma cells after suppression of GLIS3." (PMID 27172792, 2016). "Furthermore, migration of PXDN, NTN4 or GLIS3 siRNA transfected melanoma cells was inhibited following transplantation into the embryonic chicken neural tube compared to control siRNA transfected melanoma cells." (PMID 27172792, 2016). "We determined that the reduction of GLIS3 expression suppressed melanoma cell invasion in vitro." (PMID 27172792, 2016). "Elucidation of GLIS3 and its interaction partners in melanoma may provide new opportunities for the development of therapeutic strategies in the treatment of this disease." (PMID 27172792, 2016). "Our study suggests that PXDN, NTN4 and GLIS3 play a functional role in promoting melanoma cellular invasion, and therapeutic approaches directed toward inhibiting the action of these proteins may reduce the incidence or progression of metastasis in melanoma patients." (PMID 27172792, 2016). "In this study we investigated three genes consistently upregulated in mesenchymal-like melanoma cells including Peroxidasin (PXDN), Netrin 4(NTN4) and GLIS Family Zinc Finger 3 (GLIS3)." (PMID 27172792, 2016). "In TCGA melanoma dataset, mutual exclusivity data from melanoma patients revealed that both PXDN and GLIS3 are co-expressed (Odds ratio = 2.23, p = .010, Fisher's exact test)." (PMID 27172792, 2016). "Melanoma cells were transfected with siRNA targeting PXDN, NTN4 or GLIS3, cultured as a hanging drop for 24 hours and introduced into the trunk neural tube of a developing chick embryo." (PMID 27172792, 2016).
Alzheimer disease (3 papers, 2015 to 2025). A progressive, neurodegenerative disease characterized by loss of function and death of nerve cells in several areas of the brain leading to loss of cognitive function such as memory and language. "Only 1 study to date, using genome-wide association studies of cerebrospinal fluid tau levels to identify risk variants for Alzheimer disease, has identified GLIS3 as a significant locus for the development of Alzheimer disease." (PMID 26259131, 2015). "Variants in GLIS3 have also been associated with levels of tau and ptau in Alzheimer’s disease." (PMID 40529392, 2025).
cyst (3 papers, 2009 to 2026). A sac-like closed membranous structure that may be empty or contain fluid or amorphous material. "In addition, pharmacological inhibition of PKM2 with compound 3K in GLIS3-deficient spheroid cultures and Glis3-KO kidneys significantly reduced spheroid size, cyst number and cystic area." (PMID 41826646, 2026). "The development of PKD in GLIS3-deficient mice, as well as in kidney-specific knockout mice, is characterized by the formation of glomerular cysts, dilation of proximal tubules, and cyst formation in distal tubules and collecting ducts." (PMID 39505148, 2024). "Our study suggests that GLIS3 has a protective role against cyst formation and that increased expression or activation of GLIS3 may have potential for future therapeutic strategies." (PMID 39505148, 2024). "Study of an inducible GLIS3 knockout model could help to further clarify the role of GLIS3 in kidney metabolic regulation and cyst formation beyond early postnatal timepoints." (PMID 39505148, 2024). "Phosphorylation of PKM2 at Y105 and S37, which stimulate dimer formation, nuclear localization and aerobic glycolysis, is increased in Glis3-KO kidneys, consistent with a role for PKM2 in metabolic reprogramming and cyst formation." (PMID 41826646, 2026).
developmental delay (3 papers, 2015 to 2022). "For patients severely affected by GLIS3 mutations, developmental delay and learning difficulties are common features." (PMID 26259131, 2015).
exocrine pancreatic insufficiency (3 papers, 2015 to 2022). Inability of the exocrine pancreas to produce and secrete an adequate amount of digestive enzymes into the small intestine. "We describe new presenting features in patients with GLIS3 mutations, including craniosynostosis, hiatus hernia, atrial septal defect, splenic cyst, and choanal atresia and confirm further cases with sensorineural deafness and exocrine pancreatic insufficiency." (PMID 26259131, 2015).
gestational diabetes (3 papers, 2021 to 2026). Carbohydrate intolerance first diagnosed during pregnancy. "GLIS3 is one of a few genes implicated in all main types of diabetes, with the loss of GLIS3 function in mice and humans causing neonatal diabetes, and single nucleotide polymorphisms in GLIS3 associated with an increased risk for Type 1, Type 2, and gestational diabetes in humans." (PMID 41542538, 2026).
thyroid (3 papers, 2023 to 2024). "Whether the development of CH in human patients with GLIS3 deficiency is related to thyroid dysgenesis or dyshormonogenesis has been inconclusive and shown to vary among patients." (PMID 38281222, 2024). "These analyses showed that the development of CH in Glis3KO mice is due to dyshormonogenesis rather than thyroid dysgenesis and further indicated a connection between GLIS3 protein and the TSH–TSHR signaling pathway." (PMID 38281222, 2024).
autoimmune disease (2 papers, 2021). A disorder resulting from loss of function or tissue destruction of an organ or multiple organs, arising from humoral or cellular immune responses of the individual to their own tissue constituents. "In contrast to many other putative T1D risk loci, the GLIS3-associated risk is not shared with other autoimmune diseases, emphasizing its effects at the β-cell level, probably by augmenting β-cell susceptibility to immune and metabolic stressors." (PMID 33376132, 2021).
choanal atresia (2 papers, 2015 to 2022). Choanal atresia (CA) is a congenital anomaly of the posterior nasal airway characterized by the obstruction of one (unilateral) or both (bilateral) choanal aperture(s), with clinical manifestations ranging from acute respiratory distress to chronic nasal obstruction. "Patient 1 is the first patient with a GLIS3 mutation to present with choanal atresia." (PMID 26259131, 2015).
craniosynostosis (2 papers, 2015 to 2022). Craniosynostosis is defined as the premature fusion of one or more cranial sutures leading to secondary distortion of skull shape resulting in skull deformities with a variable presentation. "Patient 6 is the first patient with a mutation in GLIS3 to have sagittal craniosynostosis requiring surgical intervention." (PMID 26259131, 2015). "Patient 6 presented with craniosynostosis, which is a novel presentation in the GLIS3 phenotype." (PMID 26259131, 2015).
prostate carcinoma (2 papers, 2021 to 2023). A carcinoma that arises from epithelial cells of the prostate gland. "All this suggests that it is unlikely that JMJD2D impinges in a meaningful way on the oncogenic potential of prostate cancer cells through modulating the expression of GLIS3, RSPO3, NPR1 or OSR2." (PMID 38045004, 2023). "This would be consistent with the notion that methylation of JMJD2D could promote prostate cancer development through upregulation of CBLC and METTL27 as well as through downregulation of COL4A5, GLIS3, NPR1, OSR2, PLAGL1 and RSPO3." (PMID 38045004, 2023).
renal cystic dysplasia (2 papers, 2015 to 2017). "As previously reported, most of the patients who had GLIS3 mutations presented with renal parenchymal disease, primarily renal cystic dysplasia." (PMID 28253873, 2017). "In patients with GLIS3 mutations, most of our patients presented renal parenchymal disease, primarily renal cystic dysplasia." (PMID 26259131, 2015).
adenoma (1 paper, 2019). A neoplasm arising from the epithelium. "PAX8/GLIS3 was identified in the one hyalinizing trabecular adenoma, consistent with a recent report." (PMID 31572297, 2019).
anemia (1 paper, 2021). A reduction in the number of red blood cells, the amount of hemoglobin, and/or the volume of packed red blood cells. "Our case report is the first describing a congenital hyporegenerative anemia in a patient with a GLIS3 mutation." (PMID 33935973, 2021). "Whole exome sequencing, which was initially discussed in view of the complex phenotype including severe hyporegenerative anemia, was not pursued after confirmation of the homozygous deletion in the GLIS3 gene and later on normalization of hemoglobin levels." (PMID 33935973, 2021).
anxiety disorder (1 paper, 2024). A category of psychiatric disorders which are characterized by anxious feelings or fear often accompanied by physical symptoms associated with anxiety. "For anxiety disorders, per one-unit increase in genetically predicted log odds of T1D as measured by the GLIS3 cis instrument, there was a 46% increase in odds using our primary IVW method (OR = 1.46; 95% CI = 1.22–1.75; P < 0.001; adjusted P < 0.001)." (PMID 39263363, 2024).
carbohydrate metabolism disorders (1 paper, 2018). "We estimated frequency of rare single-nucleotide variants in the coding region of GLIS3 in a Caucasian population and among individuals with carbohydrate metabolism disorders in Russia." (PMID 29606121, 2018).
Central hypothyroidism (1 paper, 2021). A type of hypothyroidism due to an insufficient stimulation of an otherwise normal thyroid gland. "Similarly, IGSF1 (leads to central hypothyroidism), SFTA3 and GLIS3, whose mutations are linked to CH, were identified." (PMID 34249923, 2021).
Chronic colitis (1 paper, 2026). A chronic inflammatory disease of the large intestine (colon, cecum and rectum). "We further demonstrated that the magnitude of the GLIS3 gene expression program in intestinal biopsies could be used to stratify patients with ulcerative colitis by disease severity, and that fibroblast-specific deletion of Glis3 in mice alleviated pathological features of chronic colitis." (PMID 41501466, 2026).
Cirrhosis (1 paper, 2020). A chronic disorder of the liver in which liver tissue becomes scarred and is partially replaced by regenerative nodules and fibrotic tissue resulting in loss of liver function. "Mutations in the Glis3 gene have led to neonatal diabetes, thyroid and renal diseases, and liver dysfunction ranging from hepatitis to cirrhosis." (PMID 33375092, 2020).
gastric cancer (1 paper, 2023). A primary or metastatic malignant neoplasm involving the stomach. "Clinical features associated with high or low expression of GLIS3 in patients with gastric cancer." (PMID 36923439, 2023). "Therefore, we sought to examine the prognostic significance of GLIS3 and its association with immune infiltration in gastric cancer." (PMID 36923439, 2023). "Using public data from The Cancer Genome Atlas (TCGA), we investigated whether GLIS3 gene expression was linked with prognosis in patients with stomach cancer (STAD)." (PMID 36923439, 2023). "However, any association of GLIS3 with gastric cancer has hardly been carefully studied." (PMID 36923439, 2023). "We found that GLIS3 mRNA expression was upregulated in gastric cancer tissues (N=10) compared with normal gastric tissues (P<0.001)." (PMID 36923439, 2023). "Immunohistochemical results showed that GLIS3 expression was higher in gastric cancer compared to normal tissues." (PMID 36923439, 2023). "The metastatic ability of gastric cancer cells was similarly inhibited after GLIS3 silencing, as indicated by the results." (PMID 36923439, 2023). "The silencing of GLIS3 was achieved in gastric cancer cells AGS and MKN28 by transient transfection with Lipofectamine 3000 containing 1μg siRNA, and the transfection efficiency was detected by WB and qPCR after 48H collection of protein and RNA." (PMID 36923439, 2023). "We verified the expression of GLIS3 mRNA in gastric cancer tissues by quantitative qRT-PCR." (PMID 36923439, 2023). "And GLIS3 tended to show increased expression in gastric cancer." (PMID 36923439, 2023). "GLIS Family Zinc Finger 3 (GLIS3) has received scant attention in gastric cancer research." (PMID 36923439, 2023). "We analyzed the pattern of GLIS3 expression in gastric cancer and its predictive value." (PMID 36923439, 2023). "The possible prognostic impact of GLIS3 in gastric cancer has not been reported." (PMID 36923439, 2023).
hyperthyroidism (1 paper, 2024). Overactivity of the thyroid gland resulting in overproduction of thyroid hormone and increased metabolic rate. "Greater insights into the upstream pathways that regulate GLIS3 expression and/or its transcription activity might provide new therapeutic approaches in the management of hypo- and hyperthyroidism." (PMID 38281222, 2024).
insulinoma (1 paper, 2015). "Similarly, overexpression of Itch, but not the catalytically inactive mutant, in rat insulinoma INS1 832/13 cells resulted in a decrease in endogenous rIns2 mRNA expression presumably due to proteolytic degradation of endogenous Glis3." (PMID 26147758, 2015).
knee osteoarthritis (1 paper, 2022). "The GLIS3 gene have been associated with a decreased risk of knee osteoarthritis, but its relationship with muscle performance remains to be further investigated." (PMID 34792618, 2022).
liver dysfunction (1 paper, 2016). "Case 8 (GLIS3 p.F857Y) had liver dysfunction but improved by following supportive therapy." (PMID 26839896, 2016).